HIF1A (hypoxia inducible factor 1 subunit alpha)
Diseases named in the same sentence as HIF1A in open-access papers (continued):
Sharing a sentence is not in itself a finding about the gene and the disease.
renal cell carcinoma (continued). "Hypoxia-inducible factor-1α (HIF-1α) is a core factor of the HIF-1 signaling pathway and has been reported to play an important role in various biological behaviors of renal cell carcinoma." (PMID 39068456, 2024). "The Hif‐1α and PI3K‐Akt signaling pathways involved the largest number of differentially expressed proteins (n = 6), while the regulation of renal cell carcinoma had the smallest adjusted p‐value." (PMID 39670604, 2024). "METTL13 is lowly expressed in renal cell carcinoma, and knockdown of METTL13 promotes the PI3K/AKT/mTOR/HIF-1α pathway leading to migratory ability and invasiveness of renal cell carcinoma cells as well as elevated Vimentin and N-cadherin." (PMID 39289775, 2024). "We previously identified SphK1/S1P signaling as a new modulator of HIF-1α and HIF-2α activities under hypoxia in a wide array of cancer cell models (prostate, glioma, breast, lung and renal cell carcinoma) both in vitro and in vivo." (PMID 35158767, 2022). "In that respect, we previously reported that FTY720 decreases both HIF-1α and HIF-2α expression and subsequent expression of GLUT-1 and VEGF in a number of cellular and animal models of renal cell carcinoma." (PMID 35158767, 2022). "As for the regulated targets in the renal cell carcinoma pathway, TGFB1, EPAS1, HIF1A, VEGFA, KRAS, and PIK3CA regulated by miR-140 have been reported to interfere with KIRC." (PMID 35528546, 2022). "Previous studies have discovered the tumor‐suppressive activities of HIF1A and HIF2A in renal cell carcinoma and lung cancer." (PMID 34245041, 2021). "Along this line, in contrast to renal cell carcinoma cells, GLUT1 expression has also been shown to be controlled by HIF1α in Hep3B cells." (PMID 33321829, 2020). "The upregaulted gene ARNT is invovled in Hypoxia Signaling in the Cardiovascular System, Renal Cell Carcinoma Signaling, VEGF Signaling, HIF1α Signaling, Aryl Hydrocarbon Receptor Signaling and Xenobiotic Metabolism Signaling pathways." (PMID 33272211, 2020). "In renal cell carcinoma (RCC), researchers have found that high expression of TRIB3, which is induced by HIF-1α, enhanced cell proliferation, migration and invasion abilities by regulating the MAPK pathway." (PMID 32874132, 2020). "In renal cell carcinoma, it has been shown that hypoxia activates STAT3, which consequently binds to the HIF-1α promotor and contributes to the stability and synthesis of the HIF-1α protein." (PMID 27029037, 2016). "Previous studies have also shown that HIF1α inhibits mitochondrial biogenesis and reduces oxygen consumption in VHL-null renal cell carcinoma, which is consistent with our findings." (PMID 25830305, 2015). "mTORC1 promotes HIF-1α and VEGF protein and mRNA expression to induce angiogenesis in renal cell carcinoma." (PMID 25596749, 2015). "For example, deficiency of von Hippel-Lindau function counters the degradation of HIF-1α under normoxia, and HIF-1α represses the transcription of the E-cadherin gene, contributing to EMT in von Hippel-Lindau-null renal cell carcinomas." (PMID 26528854, 2015). "TCEB2, HIF1A, TCEB1, CUL2, and RBX1 were involved in the renal cell carcinoma pathway, while TCEB2, HIF1A, TCEB1, and CUL2 had the highest degree in the PPI network." (PMID 25091575, 2014). "Genes such as TCEB2, HIF1A, TCEB1, CUL2, and RBX1 were involved in both of the first and the third routes of the renal cell carcinoma pathway." (PMID 25091575, 2014). "HIF-1α binds directly to the PDK1 promoter and activates the transcription of PDK1 in human renal cell carcinoma cell lines." (PMID 23050013, 2012). "In renal cell carcinomas, VHL inactivation occurs in most sporadic cases, resulting in an accumulation of CA9, HIF-1α and HIF-2α." (PMID 15558070, 2005). "Notably, our results reveal that HIF-1α protein levels were higher than HIF-2α in primary HB cell cultures, a pattern that differs from that showed by renal cell carcinoma (RCC) carrying VHL-defective genes." (PMID 40427061, 2025).
renal cell carcinoma (continued). "Recent studies have led to treating renal cell carcinoma by specifically inhibiting transcriptional activity of HIF2α (not HIF1α) with a small molecule named PT2385 and PT2977." (PMID 38243138, 2024). "Moreover, we further proved that TGFBI participates in the EMT process of renal cell carcinoma and affects the occurrence and development of renal cancer through the PI3K/AKT/mTOR/HIF-1α signaling pathway." (PMID 39068456, 2024). "For example, in von Hippel-Lindau-defective renal cell carcinoma (RCC), HIF-1α inhibits cell proliferation in vivo or in vitro, and the knockdown of HIF-1α promotes tumor growth accordingly, while EPAS1 is shown to be essential for the growth of xenograft in RCC." (PMID 37124944, 2023). "In addition, isoflurane increased the levels of HIF-1α, HIF-2α, and VEGF in primary renal cell carcinoma." (PMID 35222023, 2022). "Transcriptional profiling of primary renal cell carcinoma revealed a correlation between HIF-2α (but not HIF-1α) and high expression of the lipid droplets coat protein perilipin 2 (PLIN2)." (PMID 34071836, 2021). "Sulforaphane, an active constituent present in broccoli and cauliflower, exhibits a potent effect against several cancers, including cervical, bladder, prostate, and renal cell carcinoma, by hitting various signaling networks, such as the STAT3/HIF-1α/VEGF and Nrf2 signaling pathways." (PMID 30871059, 2019). "Recent studies have found several factors that could regulate the metastasis of renal cell carcinoma, such as VEGF, HIF-1α, HIF-2α, HGF, and E-cadherin, yet, how these factors are regulated remains unclear." (PMID 31672157, 2019). "LncRNA HOTAIR (HOX transcript antisense RNA) regulated HIF-1α (hypoxia inducible factor 1 subunit alpha)/AXL (AXL receptor tyrosine kinase) signaling and promoted tumorigenesis through acting as a ceRNA of miR-217 in renal cell carcinoma." (PMID 30149689, 2018). "In von Hippel Lindau (VHL)-deficient renal cell carcinoma (RCC), NOX4 also promotes renal tumorigenesis in a similar signal pathway via nuclear accumulation of HIF-2α, not HIF-1α." (PMID 28594389, 2017). "The subtle change in the ratio of HIF-1α and HIF-2α in cells, via the dual functions of HAF in hypoxia, might provide a new strategy to develop a combination therapy for renal cell carcinoma." (PMID 28572533, 2017). "Genes showing a 2-fold overexpression in both the benign oncocytoma-like regions and high-grade oncocytic carcinoma regions included several notable genes such as VHL, HIF1A (hypoxia inducible factor 1), cMET, and TSC1 (tuberous sclerosis 1), which are cancer genes involved in renal cell carcinoma." (PMID 25275525, 2014). "Among the protein–protein interaction network, TCEB2, HIF1A, TCEB1, CUL2, RBX1, and PHF17 were hub genes which might be involved in the development of renal cell carcinoma." (PMID 25091575, 2014). "Genes of TCEB2, HIF1A, TCEB1, and CUL2 which participated in renal cell carcinoma pathway might be the potential target genes for RCC treatment." (PMID 25091575, 2014). "Hemangiosarcoma cell lines expressed HIF1α at approximately comparable levels to those seen in human ACHN renal cell carcinoma cells with wild type VHL (data not shown), suggesting there was no abnormal accumulation of this protein." (PMID 21062482, 2010). "While, both HIF-1α and HIF-2α have been identified as renal cell carcinoma (RCC)-related factors, involving in the development of RCC." (PMID 39748950, 2024). "In addition, in renal cell carcinoma, overexpression of TRIM21/Ro52 destabilizes hypoxia-inducible factor 1 subunit alpha (HIF-1α), leading to the suppression of aerobic glycolysis and subsequent inhibition of both in vitro and in vivo tumor cell proliferation and migration." (PMID 37993883, 2023). "Moreover, miR-217/HIF-1α/AXL signaling has been reported to be involved in lncRNA-HOTAIR-promoted renal cell carcinoma carcinogenesis, which provides a new target for the diagnosis and treatment of renal cell carcinoma." (PMID 35310917, 2022).
renal cell carcinoma (continued). "Interestingly, primary renal cell carcinoma revealed a correlation between HIF-2α (but not HIF-1α) and generation of lipid droplets (see Section 3.3)." (PMID 34071836, 2021). "Moreover, ALS2 and Rab5 activity were elevated both in a model of endogenous HIF-1α stabilization (renal cell carcinoma) and by following expression of stable non-hydroxylatable HIF-1α." (PMID 33339852, 2020). "Finally, ER-α may compete with HIF-1α for VHL-mediated ubiquitination and proteasome targeting, as reported in renal cell carcinomas." (PMID 28320353, 2017). "Paradoxically, a negative relationship between the expressions of ANXA3 and HIF1α has been reported in renal cell carcinoma (RCC)." (PMID 34355022, 2021). "HIF-1α polymorphism C1772T in human were initially identified in renal cell carcinoma patients which cause amino acid substitutions within the N-TAD, however, the difference in genotype distribution was not indicated between renal cell carcinoma cases and controls." (PMID 24015181, 2013). "PT2385 selectively binds HIF-2α (Kd < 50 nM)—but not HIF-1α—to prevent it from binding to HIF-1β and has shown promise in preclinical studies and clinical trials on patients with renal cell carcinoma." (PMID 35235351, 2022). "Endothelial HIF-2a in adult mice, but not Hif-1α, is required to maintain airway microvascular structure and function, and HIF-2α antagonist is renal cell cancer target." (PMID 36147561, 2022). "In the pathological specimens of renal cell carcinoma, there was a significant negative correlation between VASH-1 and HIF1α." (PMID 32754616, 2020). "Data from studies using paired isogenic renal cell carcinomas with non-functional (VHL null; HIF-1α/2αhigh) and functional VHL protein (VHL restored; HIF-1α/2αlow), along with siRNA of HIF, allowed us to firmly implicate the role of HIF in downregulating MHC class I expression." (PMID 29155844, 2017). "DNA microarray analysis in renal cell carcinoma cells that exclusively expressed HIF-2α (but not HIF-1α) showed that a number of hypoxia-inducible genes were expressed, including CITED2, a putative negative regulator of HIF-1α activity." (PMID 25964891, 2015). "However, in renal cell carcinomas, activation of the Notch pathway is independent of HIF-1α and HIF-2α, while in stem and precursor cells, hypoxia regulates Notch1 activity post-translationally via HIF-1α." (PMID 22363487, 2012).
non-small cell lung carcinoma (187 papers, 2006 to 2026). A group of at least three distinct histological types of lung cancer, including non-small cell squamous cell carcinoma, adenocarcinoma, and large cell carcinoma. "Starvation-induced lncRNA AC020978 promoted the proliferation of non-small cell lung cancer through the PKM2 / HIF-1α axis, causing higher invasiveness." (PMID 37341994, 2023). "We investigated the association between single nucleotide polymorphisms (SNPs) in the HIF1A gene and the prognosis of advanced non-small cell lung cancer (NSCLC) patients undergoing radiation therapy." (PMID 33621198, 2021). "A tight association between HIF1α expression and poor prognosis and survival has been reported in different cancers including colorectal cancer, non-small-cell lung cancer (NSCLC) and pancreatic ductal adenocarcinomas patients." (PMID 33572152, 2021). "Over-expression of HIF1α caused by intratumoral hypoxia and its genetic alterations are associated with increased mortality in several cancer types including non-small-cell lung cancer (NSCLC)." (PMID 24567056, 2014). "For example, associations between HIF-1α overexpression and decreased mortality have been reported for patients with head and neck cancer and non-small cell lung cancer." (PMID 21843314, 2011). "The lncRNA ASLNC12089 functions as a ceRNA in non-small cell lung cancer, competing with HIF-1α mRNAs and the HIF-1α chaperone protein (HIF1AN) for binding to miRNAs via common miRNA response elements (MREs)." (PMID 41614928, 2026). "Canagliflozin, through AMPK activation and mTOR inhibition, downregulates HIF-1α, hence inhibiting the proliferation of non-small cell lung cancer (NSCLC) and improving the efficacy of radiation therapy." (PMID 40439888, 2025). "The article “Expression of CD82/KAI1 and HIF-1α in non-small cell lung cancer and their relationship to vascular mimicry” was the one article from our sample, published in Chinese." (PMID 40786517, 2025). "In non-small cell lung cancer, USP38, upon binding with HIF-1α, removes the K11-linked polyubiquitin chains at Lys 769 of HIF-1α, preventing its proteasomal degradation and thereby maintaining the stability of the HIF-1α protein." (PMID 40936898, 2025). "For instance, HIF-1α can improve the resistance of non-small-cell lung cancer to chemotherapeutic agents by inhibiting ferroptosis." (PMID 41154694, 2025). "In non-small cell lung cancer, casticin and Coenzyme Q0 (CoQ0) suppress HIF-1α signaling, leading to reduced PKM2 expression, inhibition of glucose metabolism, and reversal of the Warburg effect." (PMID 40842995, 2025). "Under hypoxia, the long noncoding RNA AC020978 promotes the nuclear translocation of PKM2, regulates PKM2-enhanced HIF-1α transcription activity and indicates an aggressive phenotype of non-small cell lung cancer (NSCLC)." (PMID 40563308, 2025). "In conclusion, our study provides valuable insights into the interplay between PD-L1 expression, HIF-1α expression, and KRAS mutation status in non-small cell lung cancer (NSCLC), particularly in KRAS G12C mutant cases." (PMID 39996842, 2025). "MARK kinases, members of the AMPK-related kinase family, potentiate the AMPKα1/mTOR/HIF-1α signaling axis, contributing to the Warburg effect and cell proliferation in non-small cell lung cancer." (PMID 39575238, 2024). "Another study found that TRPV3 facilitated angiogenesis via the HIF-1α-VEGF signaling pathway in non-small-cell lung cancer." (PMID 39469202, 2024). "In non-small cell lung cancer, hypoxia-inducible factor (HIF)-1α inhibits ferroptosis by activating the Hippo–YAP signaling pathway, and YAP1 upregulates GPX4 expression." (PMID 37773303, 2024). "Studies have reported that the instability of HIF-1α in non-small cell lung cancer cells diminishes their vulnerability to ferroptosis." (PMID 39944353, 2024). "HIF-1α is also involved in drug resistance in several solid tumors, including non-small cell lung cancer." (PMID 37434755, 2023).
non-small cell lung carcinoma (continued). "They found that the expression of EGLN2 was negatively correlated with HIF1A in non-small cell lung cancer." (PMID 37553713, 2023). "Another study proposed that upregulation of Notch pathway by radiation confers to radioresistance in non-small cell lung cancer cell lines through the activation of HIF-1α." (PMID 37460927, 2023). "ESM1 can also promote the development of non-small cell lung cancer by regulating the expression of HIF1α." (PMID 38201620, 2023). "For instance, the prognostic value of HIF1A in non-small cell lung cancer is altered with EGLN2 expression, and gene signature associated with T cell dysfunction can be screened by assessing G × G interactions." (PMID 37553713, 2023). "NUDT21 has recently been confirmed as a HIF1α responsive target, accounting for hypoxia-induced loss of NUDT21 in non-small cell lung cancer cells." (PMID 35671866, 2022). "Under chronic hypoxia conditions, NR4A1 has low expression in non-small cell lung cancer (NSCLC) cells by the mediation of HIF-1α, involved in hypoxia-induced apoptosis resistance." (PMID 36052242, 2022). "EGF was shown to induce the expression of CXC Chemokine Receptor 4 (CXCR4) and promote migration in normoxic non-small cell lung cancer (NSCLC) cells via HIF-1α and the PI3K/AKT and mTOR pathways." (PMID 35158804, 2022). "It has been reported that upregulation of HIF-1α and overexpressed VEGF are associated with higher cellular proliferation, specifically for several non-small-cell lung cancers." (PMID 36291910, 2022). "Hypoxia induces the stabilization of Hif-1α, which suppresses PPARγ in non-small-cell lung cancer (NSCLC)." (PMID 35954274, 2022). "Recent research indicated that high expression of miR-224 in CAFs facilitated proliferation, EMT and metastasis of non-small cell lung cancer cells by the SIRT3/AMPK/mTOR/ HIF1α signaling pathway." (PMID 35589690, 2022). "miRNA-21 combined with cisplatin inhibits glycolysis and induces cell death through the PI3K/AKT/mTOR/HIF-1α pathway, improves the cytotoxicity of cisplatin, and provides a theoretical basis for the treatment of cisplatin-resistant non-small cell lung cancer." (PMID 34046349, 2021). "The OLFM4/HIF-1α axis was found to be involved in the regulation of hypoxia-induced invasion, epithelial-mesenchymal transition, and chemotherapy resistance in non-small-cell lung cancer." (PMID 34912753, 2021). "In AGP-based treatment, down regulation of PI3K/AKT signaling pathway has been observed that accordingly reduce the expression of HIF-1α, a factor for tumor growth in non-small cell lung cancer (NSCLC) by the ubiquitin-dependent degradation." (PMID 34795581, 2021). "In non-small-cell lung cancer cells, inhibition of the HIF-1α/VEGF signaling pathway by GLA inhibits the hypoxia-induced cell invasion and proliferation." (PMID 34201062, 2021). "CircPIP5K1A enhances metastasis and proliferation of non-small cell lung cancer by the regulation of miR-600/HIF-1α." (PMID 34774083, 2021). "A previous study showed in non-small cell lung cancer cells (NSCLC) that Ak4 stabilizes Hif1α protein through inhibition of prolyl hydroxylase (PHD), our data suggest that Ak4 not only stabilizes Hif1α protein but also enhances its transcription." (PMID 33790902, 2021). "Here we showed that exposure to chemotherapeutic drug etoposide induces an exacerbation of ROS production which activates HIF-1α-mediated the metabolic reprogramming toward increased glycolysis and lactate production in non-small cell lung cancer (NSCLC)." (PMID 33097055, 2020). "MiR-206 can attenuate the growth and angiogenesis of non-small-cell lung cancer cells through the 14-3-3z/STAT3/HIF-1α/VEGF pathway." (PMID 32014012, 2020). "This study was conducted with the main objective of investigating the potential role of miR-320a in radioresistance of non-small cell lung cancer (NSCLC) via the possible mechanism related to HIF1α, KDM5B, and PTEN." (PMID 33304897, 2020).